KLF4 (KLF transcription factor 4)
Diseases named in the same sentence as KLF4 in open-access papers (continued):
Sharing a sentence is not in itself a finding about the gene and the disease.
hepatocellular carcinoma (66 papers, 2012 to 2025). A malignant tumor that arises from hepatocytes. "High cytoplasmic expression of KLF4 was associated with better disease-specific survival and was an independently favorable prognostic factor in hepatocellular carcinoma." (PMID 24897024, 2014). "KLF4 may suppress the initiation and progression of hepatocellular carcinoma (HCC), with its expression levels closely linked to patient prognosis." (PMID 39995670, 2025). "Thus, KLF4 is expected to be a diagnostic and prognostic biomarker for colorectal, gastric and hepatocellular carcinomas." (PMID 37031197, 2023). "KLF4 has been shown to be a tumor suppressor in a variety of malignancies, and reduced KLF4 expression has been linked to a worse overall survival rate in hepatocellular carcinoma, pancreatic cancer, and renal cell carcinoma." (PMID 35345512, 2022). "In liver cancer, miR-206 targets KLF4, suppressing its expression and promoting M1 macrophage polarization, thereby effectively preventing hepatocellular carcinoma." (PMID 39995670, 2025). "The demonstration that KLF4 transcription is modulated through epigenetic mechanisms has been obtained also in hepatocellular carcinoma (HCC)." (PMID 39135777, 2024). "Numerous studies have demonstrated that KLF4 inhibits the progression of colorectal, gastric, and hepatocellular carcinomas, and low KLF4 expression is clearly related to poor overall survival." (PMID 37031197, 2023). "This study aimed to investigate the role of deubiquitinating enzyme 3 (DUB3) in the regulation of Krüppel-like factor 4 (KLF4) expression in hepatocellular carcinoma (HCC)." (PMID 35383144, 2022). "KLF4 can reprogram of differentiated cells into pluripotent embryonic stem cells, and combats tumor growth and chemoresistance in hepatocellular carcinoma." (PMID 35794546, 2022). "RNA helicases also have known roles in cancer; in particular, DDX5 promotes GC cell proliferation, and DDX17 hepatocellular carcinoma progression via inhibiting Klf4 transcriptional activity." (PMID 35566209, 2022). "In hepatocellular carcinoma, KLF4 directly activated EpCAM, increased the number of EpCAM+/CD133+ liver cancer stem cells in vitro, and amplified the tumorigenesis in vivo." (PMID 34680284, 2021). "In hepatocellular carcinoma (HCC), the loss of KLF4 expression is closely correlated with cancer progression and reduced overall survival." (PMID 34114341, 2021). "According to the latest findings, in hepatocellular carcinoma (HCC) KLF4 performs a tumor suppressive role." (PMID 33266506, 2020). "DDX17 promotes the formation of hepatocellular carcinoma by inhibiting Klf4 transcriptional activity." (PMID 33000861, 2020). "As SET8 interacted with KLF4, we tended to see if KLF4 affected the effect of SET8 in hepatocellular carcinoma cells." (PMID 30952833, 2019). "KLF4 was also found to mediate cisplatin resistance in the hepatocellular carcinoma stem-like cells by upregulating expression of gamma-glutamylcysteine synthetase and the subsequent glutathione synthesis." (PMID 31427673, 2019). "Three of them (i.e., Pik3cd, Klf4, Hoxb5) were excluded through analysis of their expression in hepatoma cells transfected with the sja-miR-7-5p mimics." (PMID 30967999, 2019). "Conversely, the MET induced by the enforced reexpression of the putative tumor suppressor KLF4 in hepatocellular carcinoma cells was accompanied by VDR upregulation and an increase in the inhibitory effect of 1,25(OH)2D3 on cell proliferation." (PMID 26880977, 2016). "KLF-4 has been recently recognized to be downregulated during renal fibrosis and functions as a suppressor of renal fibrogenesis, and the antifibrosis effect of KLF-4 has also been recognized in hepatocellular carcinoma cells." (PMID 26839446, 2015).
hepatocellular carcinoma (continued). "For example, it was shown that TRAF7 associated with KLF4 through its ZF-CC region and was responsible for ubiquitination and proteasome-dependent degradation of KLF4 through its RING-dependent E3 ubiquitin ligase activity to promote hepatocellular carcinoma progression." (PMID 37583551, 2023). "miR-9-5p downregulated Klf4 expression and influenced the progression of hepatocellular carcinoma." (PMID 35336829, 2022). "In the present study, we determined that miR-18a is aberrantly upregulated in HCC and promotes hepatocellular carcinoma cell motility by inhibiting KLF4, implying that miR-18a may play a positive role in the regulation of human HCC progression." (PMID 28978114, 2017). "Many groups reported that KLF4 acts as an anti-oncogene against various cancers including bladder, colorectal, gastric, pancreas, esophageal, lung, prostate, and hepatocellular carcinoma." (PMID 28380435, 2017). "Therefore, our findings were consistent in supporting the functional significance of TGF-β1 down-regulating KLF4 by activating miR-135a-5p in hepatocellular carcinoma." (PMID 27302923, 2016). "And the anti-EMT effect of KLF-4 has also been recognized in hepatocellular carcinoma cells." (PMID 26839446, 2015). "So far, it is known that KLF4 acts as a tumor suppressor by positively regulating the levels of E-cadherin in hepatocellular carcinoma, MMP-2 and MMP-9 metalloproteases in neuroblastoma and the TF Slug during the epithelial to mesenchymal transition of mammary epithelial cells." (PMID 25181544, 2014). "This study investigates the role of Kruppel-like factor 4 (KLF4), a transcription factor, as a tumor suppressor in hepatocellular carcinoma (HCC) by regulating ATP synthesis." (PMID 39000273, 2024). "To assess the biological functions of KLF4 in hepatocellular carcinoma (HCC), we initially examined the expression levels of KLF4 in HCC cell lines." (PMID 39000273, 2024). "In hepatocellular carcinoma (HCC), Klf4 was shown to regulate the expression of CD9/CD81, exosomal tetraspanin surface proteins that mediate cellular interaction and have been found to be involved in cancer." (PMID 34195082, 2021). "Aberrant expression of SF3B4 was demonstrated to modulate the expression of cell cycle and EMT proteins through spliceosome effects on the tumor suppressor kruppel-like factor 4 (KLF4) in hepatocellular carcinoma (HCC)." (PMID 32346127, 2020). "This research aimed to explore the prognostic significance of KLF4 in hepatocellular carcinoma’s (HCC) patients after curative resection and the role of KLF4 in HCC progression." (PMID 32756012, 2020). "miR-18a was found to be significantly upregulated in HCC and promotes hepatocellular carcinoma cell motility by inhibiting KLF4." (PMID 28978114, 2017). "In contrast, miR-18a inhibitor significantly increased the expression of p21 in parallel with an enhanced KLF4 level, indicating that miR-18a may promote hepatocellular carcinoma cell growth and invasion by regulating the activity of KLF4 as well as downstream p21." (PMID 28978114, 2017). "Additionally, other research has shown that TRAF7 influences KLF4 by interacting with its N-terminus and promoting its degradation through ubiquitination in hepatocellular carcinoma (HCC)." (PMID 40181456, 2025). "In hepatocellular carcinoma, splicing factor 3B subunit 4 (SF3B4), a component of the spliceosome, facilitates the generation of KLF4 exon-skipping isoforms and contributes to the malignant transformation and growth of hepatocytes." (PMID 40552304, 2025). "KLF4 exhibits high levels of DNA methylation in hepatocellular carcinoma, while HDAC3 inhibits KLF4 promoter activity in lung tumors." (PMID 38584203, 2024). "KLF4 plays a role in inhibiting the development of hepatocellular carcinoma (HCC)." (PMID 37031197, 2023).
hepatocellular carcinoma (continued). "The SET8/KLF4 complex formation negatively affects the transcriptional activation of SIRT4 by KLF4, thus promoting the proliferation-favorable Warburg effect of hepatocellular carcinoma cells." (PMID 37835497, 2023). "In the present work, we aimed to investigate whether KLF4 regulates the expression of exosomal surface proteins and their roles in human hepatocellular carcinoma (HCC)." (PMID 32350244, 2020). "In this respect, KLF4 exon 3 has been recently proposed to be a prominent SF3B4 target, potentially acting in early-stage hepatocellular carcinomas." (PMID 32664474, 2020). "While our studies indicate that KLF4 represses the expression of EGFR, Liu and colleagues have recently reported that KLF4 can stimulate EGFR gene expression in hepatocellular carcinoma cells." (PMID 32552913, 2020). "Down-regulation of NANOG in human hepatocellular carcinoma decreases the expression of SOX2, OCT4, and KLF4, giving rise to the reduced proliferation, invasion, and migration of cancer cells[34 ▶]." (PMID 32429647, 2020). "In this study, we found that KLF4 is a potential direct target of miR-18a with a binding site in the 3’-UTR and investigated the role of miR-18a in regulating hepatocellular carcinoma cell proliferation and migration." (PMID 28978114, 2017). "Increased miR-18a level plays a positive role in hepatocellular carcinoma by promoting the proliferation and migration of HCC cells through targeting downstream KLF4 and p21." (PMID 28978114, 2017). "Moreover, KLF4 protein expression was decreased or lost in hepatocellular carcinoma (HCC) tissues and, in particular, lymph node metastases when compared with that in normal liver." (PMID 26087183, 2015). "Consistent with previous studies, we have found that CD133 (+) hepatocellular cancer cells highly express stemness genes (CD44, EpCAM, Oct4 and KLF4) and exhibit increased sphere formation capacity compared to the CD133 (−) cells." (PMID 26506419, 2015). "However, the role of KLF4 in hepatocellular carcinoma (HCC) remains unclear." (PMID 22937066, 2012). "Overexpression of SF3B4 in cancer cells also caused mis-splicing of Kruppel-like factor 4 (KLF4), a tumor suppressor-encoding gene, resulting in a non-functional transcript, and therefore promoting carcinogenesis in hepatocellular carcinoma." (PMID 37568815, 2023). "In hepatocellular carcinoma (HCC), KLF4 has been considered as a tumour suppressor, although the mechanism underlying its action remains largely unknown." (PMID 34114341, 2021). "In addition, KLF4 transactivated hepatocyte nuclear factor 6 (HNF-6) expression to block the dedifferentiation and progression of hepatocellular carcinoma." (PMID 32756012, 2020). "In Hepatocellular Carcinoma (HCC), the function of KLF4 has been characterized as tumor suppressor." (PMID 27302923, 2016). "As a result, KLF4 and VDR protein expression correlate directly in human hepatocellular carcinoma." (PMID 26880977, 2016). "This study aims to investigate the relationship between KLF4 and CD9/CD81 in hepatocellular carcinoma (HCC)." (PMID 32350244, 2020). "Kruppel-like factor 4 (KLF4), a member of the KLF family of transcription factors, has been considered as a crucial tumor suppressor in hepatocellular carcinoma (HCC)." (PMID 26087183, 2015).
prostate carcinoma (66 papers, 2009 to 2026). A carcinoma that arises from epithelial cells of the prostate gland. "The removal of CD8+ T cells eliminates the inhibitory effects of KLF4 deficiency on prostate cancer growth." (PMID 39995670, 2025). "Polymorphism rs817826, located between the RAD23B and KLF4 genes, has been identified as being associated with prostate cancer susceptibility though a mechanism is yet to be realized." (PMID 41413636, 2025). "Restoration of microRNA-7 suppresses KLF4 (Kruppel-like factor 4 )/PI3K/Akt/p21 pathway in prostate cancer cells, causing decreased tumorigenesis and inhibition in stemness of prostate CSCs." (PMID 31416295, 2019). "KLF4 has been associated with either oncogenic properties, such as in osteosarcoma, either with tumor suppressive functions, such as in the lung, gastric, and prostate cancers." (PMID 33640491, 2021). "In addition, the loss of IGF2 imprinting was associated with esophageal adenocarcinoma, while the hypomethylation of one of the IGF2 promoters caused dysfunction in the transcriptional regulator Kruppel-like factor 4 (KLF4) in humane prostate cancer." (PMID 32075092, 2020). "Next, we determined whether miR-1 levels are associated with KLF4 expression in prostate cancer." (PMID 27991915, 2016). "For instance, in prostate cancer, miR‐7, miR‐148‐3p, and miR‐152‐3p function as upstream regulators that downregulate KLF4 expression, thereby inhibiting cancer cell proliferation." (PMID 41532367, 2026). "Silencing of LINC00673 in prostate cancer cells demethylates the kruppel-like factor 4 (KLF4) gene promoter, inhibiting proliferation and reducing resistance to paclitaxel." (PMID 40078288, 2025). "The current study extended the list of cancers involving oncogenic roles of KLF4 from lung, breast, and prostate cancers to CRC." (PMID 40066228, 2025). "Further studies have found that androgen receptors effectively activate KLF4 and reduce the proliferation, invasion and bone metastasis of prostate cancer cells." (PMID 37031197, 2023). "Preclinical studies have also verified that KLF4 inhibits the growth and migration of prostate cancer cells." (PMID 37031197, 2023). "For instance, the expression of KLF4 is decreased in primary and metastatic prostate cancer tissues." (PMID 37031197, 2023). "Some non-coding RNAs such as miR-148-3p and miR-152-3p inhibited prostate cancer progression by downregulating KLF4 expression." (PMID 37031197, 2023). "In prostate cancer, KLF4 appears to inhibit the progression of advanced prostate cancer, but promotes the development of early prostate cancer." (PMID 37031197, 2023). "This overexpression significantly reduced the methylation level of H3K4, which in turn reduced the expression level of the KLF4 and E-cadherin genes, which suppress tumor cell proliferation, and made prostate cancer more invasive." (PMID 35493099, 2022). "For example, DNMT1 induces histone demethylation of H3K9me3 and H3K27me3 on the promoters of Zeb2 and KLF4 in prostate cancer cells." (PMID 33616161, 2021). "In prostate cancer, KLF4 transcription and KLF4 protein levels were decreased in metastases, while its re-expression inhibited prostate cancer cell migration and invasion." (PMID 33640491, 2021). "Methylation specific PCR was performed to identify methylation of the KLF4 gene promoter in prostate cancer tissues, and it was found that KLF4 was highly methylated in prostate cancer tissues compared with adjacent normal tissues (P < .05)." (PMID 31881124, 2020). "Ectopic expression of KLF4 in androgen-independent prostate cancer cells induces AR expression and decreases cell proliferation, invasion and metastasis." (PMID 33266506, 2020). "Here, this study aimed to explore the possible role of LINC00673 in prostate cancer via KLF4 gene promoter methylation." (PMID 31881124, 2020). "miR-7 can inhibit the stemness of prostate cancer stem-like cells and tumorigenesis by repressing the KLF4/PI3K/Akt/p21 pathway." (PMID 32117463, 2020).
prostate carcinoma (continued). "This anti-tumorigenic effect of KLF4 can also be observed in the prostate cancer cells after bone metastasis." (PMID 33266506, 2020). "In prostate cancer this feedback loop is dysregulated due to the disrupted miR-7 processing, which leads to the overexpression of KLF4, maintaining stemness of prostate cancer stem cells to promote tumor growth." (PMID 33266506, 2020). "Some reports indicate that KLF4 promotes prostate cancer growth while other reports claim the opposite." (PMID 33266506, 2020). "Recently, long non‐coding RNAs (lncRNAs) and Kruppel‐like factor 4 (KLF4) have been reported to participate in the biology of multiple cancers including prostate cancer." (PMID 31881124, 2020). "In prostate cancer, the expression of KLF4 is regulated by miR-7, miR-32-5p, miR-148-3p and miR-152-3p." (PMID 33266506, 2020). "Initial microarray‐based analyses indicated that both LINC00673 and KLF4 are differentially expressed in prostate cancer tissues." (PMID 31881124, 2020). "Tumor subtypes are also important; for example, in prostate cancer KLF4 is highly expressed in indolent tumors where it impedes tumor progression, while it is absent from aggressive prostate tumors." (PMID 33266506, 2020). "Next, we shifted our focus on elucidating the mechanism by which LINC00673 influenced prostate cancer cell proliferation by regulating KLF4 methylation." (PMID 31881124, 2020). "Overexpression of KLF4 inhibited proliferation and migration, induced cell cycle arrest and increased E-cadherin expression in prostate cancer cells." (PMID 33266506, 2020). "Lysine (K)-specific methyltransferase 2D (KMT2D) is yet another epigenetic modifier that negatively regulates the expression of KLF4 in prostate cancer." (PMID 33266506, 2020). "Originally, we uncovered that LINC00673 was highly expressed while KLF4 was poorly expressed in both prostate cancer tissues and cell lines." (PMID 31881124, 2020). "Accordingly, we performed in vivo and in vitro assays in the current study aiming to explore how LINC00673 influences the development of prostate cancer via regulation of KLF4." (PMID 31881124, 2020). "Some research teams discovered that KLF4 is upregulated in prostate tumor samples while other reports claim that the levels of KLF4 are in fact reduced in prostate cancer." (PMID 33266506, 2020). "It was found that LINC00673 was highly expressed, while KLF4 was poorly expressed in prostate cancer tissues." (PMID 31881124, 2020). "CD11b+ myeloid cells were isolated from Hi-Myc prostate cancers 21 days after inoculation into Klf4(f/f) or Klf4(f/f);Lys-Cre recipients." (PMID 29324844, 2018). "In this study, we found that KLF4 expression was induced by cisplatin in prostate cancer cells and increased levels of KLF4 promoted cell apoptosis." (PMID 30176890, 2018). "The downregulation of miR-32-5p in response to cisplatin treatment promoted an increase in KLF4 expression and in the sensitivity of prostate cancer to cisplatin." (PMID 30176890, 2018). "Here, we found that KLF4 was induced by cisplatin in prostate cancer cells and that the increase in KLF4 promoted cell apoptosis." (PMID 30176890, 2018). "(OCT4, 19%; SOX2, 29%; NANOG, 14%; LIN28A, 9%; KLF4, 29%); the SOX2 and KLF4 genes were amplified predominantly in prostate cancer." (PMID 30287838, 2018). "Conversely, escalating apoptosis and diminishing cell viability was observed in prostate cancer cells overexpressing exogenous KLF4." (PMID 30176890, 2018). "The potential molecular mechanism of KLF4 in regulating prostate cancer chemosensitivity was investigated by RNA sequencing analysis, q-RT-PCR, western blotting and chromatin immunoprecipitation (ChIP)." (PMID 30176890, 2018). "In this study, we found that the protein levels of KLF4 were elevated by cisplatin in prostate cancer cells and increased KLF4 expression enhanced the chemosensitivity to cisplatin." (PMID 30176890, 2018).